ATG5 (autophagy related 5)
Diseases named in the same sentence as ATG5 in open-access papers (continued):
Sharing a sentence is not in itself a finding about the gene and the disease.
infection (continued). "Upon infection or Rapa treatment, Atg5 expression was decreased and the LC3-II/LC3-I ratio increased in U87-MG cells." (PMID 28934149, 2017). "The rate of infection (% intracellular viable P. acnes) in Raw264.7, Atg5+/+ MEF, and HeLa cells was compared in the same experiment by colony assay at 5, 24, 48, and 72 h after P. acnes infection at an MOI 100 or 1000." (PMID 27219015, 2016). "The rate of infection (% intracellular viable P. acnes) was 2.8 and 2.2 times higher at 24 h, and 25.3 and 17.6 times higher at 48 h in the Atg5-/- than Atg5+/+ MEF cells at MOI 100 and 1000, respectively." (PMID 27219015, 2016). "The production of ROS in ATG5 or ATG12 siRNA group was significantly higher than that of control siRNA group upon infection with the F. nucleatum." (PMID 27828984, 2016). "Using quantitative real-time RT-PCR, we demonstrate that genes encoding for Atg5, LC3B, hVps34, UVRAG, and STX17 are significantly up-regulated 6 h post-infection." (PMID 27242971, 2016). "There was a significant decrease in the infection rate of Huh7-GFP cells that were close-contact co-cultured with DENV-infected Atg5-siRNA donor." (PMID 27558165, 2016). "The clearance of phagocytized bacteria was also dampened by inhibiting Atg5 or Beclin1 in AMs upon Pa infection." (PMID 26735693, 2016). "Atg5 or Beclin1 has little effect on cell viability upon Pa infection; however, phagocytosis was inhibited by down-regulating these two genes." (PMID 26735693, 2016). "Second, using ATG5−/− cells, we assessed the importance of autophagy for infection at various time points and under infection with various MOIs." (PMID 26248741, 2015). "Then we infected WT or ATG5−/− MEFs with HSV-2-GFP at various multiplicities of infection (MOIs) and assessed the infection with fluorescence microscopy." (PMID 26248741, 2015). "Compared to WT cells, ATG5−/− cells showed significantly lower viral yields and seemed highly resistant to infection." (PMID 26248741, 2015). "Downregulation of ATG5 expression in BMDM by transfection with specific siRNA prior to infection resulted in significantly decreased ATG5 levels and increased the infection rate significantly at 48 h p.i.." (PMID 26226952, 2015). "Fibroblasts from Atg5−/− autophagy deficient mice were significantly less infectable with murine prions than the wild-type fibroblasts and re-introduction of Atg5 via lentiviral transduction improved the infection rate in Atg5−/− mice." (PMID 26694349, 2015). "We found that while WT MEFs showed signs of robust HSV-2 infection, including viral gene expression, viral spread, and syncytia formation, ATG5−/− cells showed extremely reduced infection signs at all the MOIs tested." (PMID 26248741, 2015). "The elevated expression of Atg5 and beclin-1 by D39 infection was significantly decreased by NAC treatment." (PMID 26683708, 2015). "The IcsB-mediated inhibition of autophagy that occurs at later times during infection (4–6 hr) involves IcsB binding to the Shigella surface protein IcsA, which blocks IcsA recognition by the pro-autophagy factor Atg5." (PMID 24722587, 2014). "It was demonstrated that the band density of NOD1 continuously increased after prolonged infection by P. aeruginosa, while other autophagy proteins (e.g. NOD2, Beclin1 or Atg5) had the same band density even after prolonged infection." (PMID 25433669, 2014). "IcsB has previously been demonstrated to be required for S. flexneri evasion of autophagy at late times during infection (4–6 hr) by inhibiting binding of the autophagy protein Atg5 to the Shigella surface protein IcsA (VirG)." (PMID 24722587, 2014). "We also observed a marginal increase in IL-1β release from Atg5-knockdown BMMs compared with that from control cells after infection with ΔtdhASΔvopQ." (PMID 23357873, 2013). "Our results implied that promoter activity was enhanced as the infection proceeded, and disruption of Atg5 and Atg7 function further accelerated the activity." (PMID 23320079, 2013).
infection (continued). "First, we performed kinetics studies and, in accordance with our previous report, we found a strong impairment in Ed-MeV particle formation 24 hours to 72 hours post-infection in cells with a reduced expression of ATG5, as compared to control cells." (PMID 24086130, 2013). "Caspase-1 activation and the processing/release of IL-1β upon infection with ΔtdhAS were partially but significantly enhanced by the knockdown of ATG5." (PMID 23357873, 2013). "Autophagy-inhibited DLM8 and K7M3 metastatic murine OS cell lines were generated by infection with lentiviral shRNA directed against the essential autophagy protein ATG5." (PMID 24160177, 2013). "To determine if canonical autophagy was induced in addition to ATG5-independent autophagy during infection with F. tularensis, we analyzed infected MEFs that were transiently transfected with a GFP-LC3 plasmid for an increase in GFP-LC3 puncta." (PMID 23966861, 2013). "F. tularensis induces ATG5-independent autophagy while canonical autophagy remains at basal levels during infection." (PMID 23966861, 2013). "In contrast, independent studies reported that the IFN-α response to infection with ssRNA virus (i.e., vesicular stomatitis virus) was compromised in Atg5 −/− chimeric mice and in Atg5 −/− dendritic cells." (PMID 22190939, 2011). "The effect of ATG5 knockout on SARS-CoV-2 RNA counts was investigated by RT-qPCR at 2 and 6 h post-infection to assess whether ATG5 deletion causes any defects in genome replication due to impacting virus uptake." (PMID 40167317, 2025). "Experimental models, including human macrophages and murine systems, demonstrate that genetic ablation of autophagy-related genes (ARGs) such as ATG5 and ATG7 exacerbates Mtb replication and promotes necroptotic cell death, rendering hosts more susceptible to infection." (PMID 40487315, 2025). "Notably, the concurrent enhancement of NT‐GSDMD levels was observed alongside increased caspase‐1 cleavage in Atg5 conditional knockout mice during infection." (PMID 40529614, 2025). "We also investigated the impact of VgrG2 on the mTOR signaling pathway by examining the transcription levels of key genes, including mTOR, ULK1, Beclin-1, P62, LC3, Atg3, Atg5, and Atg12, following infection, and assessed the expression of the autophagy marker protein LC3-II." (PMID 40266908, 2025). "Specifically, ATG5 KO-dependent GLUT1 miss-sorting may be one of the contributors to increased M. tuberculosis pathogenesis in infection sites." (PMID 39026874, 2024). "After infection, SlATG5 expression was upregulated, indicating its involvement in the response to B. cinerea, consistent with the increased transcript level of ATG5 in Arabidopsis after inoculation with B. cinerea." (PMID 37509842, 2023). "RBAC can also stimulate cytokine secretion in macrophages, especially TNF-α and IL-6, to initiate inflammation during infection and activate autophagy-related proteins (Beclin-1, Atg5, Atg12, Atg16L) for clearing cellular debris and regulating inflammatory responses." (PMID 37687141, 2023). "In addition, immunoblot analysis showed that the levels of LC3II and ATG5 were significantly promoted, while p62 was significantly decreased, at 48 h post-infection (hpi), with overexpressing CH25H before ALV-J virus infection." (PMID 36875122, 2023). "Therefore, we further detected the expression levels of Beclin1, Atg5, and Atg7 at 8 h after infection, and found that the levels of these three autophagy-related proteins in BCG-infected macrophages were higher than those in the blank group (p < 0.05)." (PMID 37256106, 2023). "To further investigate whether ROS-mediated autophagy in Herp-KO Raw264.7 cells affects the intracellular survival of H37Ra, we examined the impact of autophagy-related 5 (Atg5) in both WT Raw264.7 cells and Herp-KO Raw264.7 cells during H37Ra infection." (PMID 37800958, 2023).
infection (continued). "Additionally, we performed infections in cells depleted of ATG16L or ATG5, two critical factors for synthesis of the autophagosome precursor." (PMID 36622177, 2023). "To determine whether LM induced an increase in autophagy-related gene expression in B16F10 cells, we detected the relative expression of Atg3, Atg5, Beclin-1, and p62 mRNA at 4 h post-infection by real-time PCR." (PMID 36838373, 2023). "Silencing RNF213, Atg5, Atg7, Atg16L1, or galectin or pharmacological inhibition of autophagy increases Salmonella replication, suggesting that autophagy and degradation in lysosomes protect cells from infection." (PMID 36288298, 2022). "Interestingly, the 23-(S)-2-amino-3-phenylpropanoyl derivative of silybin also blocks viral replication by impeding formation of the Atg5-Atg12/Atg16L complex and amplifying infection-induced autophagy." (PMID 36014565, 2022). "IcsB blocks LC3 recruitment by blocking the binding of the ATG5 to the S. flexneri surface protein VirG, allowing bacteria to escape from host cells at the late stage of infection and from liposomes during secondary infection, thereby achieving bacterial spread between cells." (PMID 36014984, 2022). "australis infection differentially regulated a significant number of genes in bone marrow-derived macrophages (BMMs) in an Atg5-depdent fashion as determined by RNA sequencing and Ingenuity Pathway Analysis, including genes in the molecular networks of IL-1 family cytokines and PI3K-Akt-mTOR." (PMID 33912163, 2021). "As expected, Atg5 or p62 deficiency led to an increase in IFN-β promoter activity and ISG56 transcription in poly I:C-treated cells in the presence of CA16 infection." (PMID 32082291, 2020). "The survival of Atg5-deficient mice infected with a dose of 5 × 105 CFU/mouse was 70% (MTTD = 7.5 days), while in the control group of mice was 0% leading to death between 4 and 10 days post infection (MTTD = 6 days) (p < 0.0001)." (PMID 33036147, 2020). "The intradermal infection of Atg5-deficient mice using the dose of 5 × 106 CFU/mouse resulted in 50% survival during the 15 days observation (MTTD = 7 days) Thus, for the Atg5-deficient mice, the LD50 was 5 × 106 CFU/mouse." (PMID 33036147, 2020). "The highest number of bacteria was observed at 72 h after infection in the liver of the control mice (2 × 106 CFU/mL), while the number of the bacteria in the liver of the Atg5-deficient mice was 2 × 104 CFU/mL, the same as the initial dose of infection (p = 0.003) (n = 3)." (PMID 33036147, 2020). "Therefore, our data suggest that Atg5 contributes to the intracellular infection of R. australis in primary mouse macrophages in close association with downregulation of the inhibitory effect on rickettsiae mediated by autocrine-secreted IL-1β." (PMID 30297526, 2019). "Similarly, in Western blot, infection with active Legionella reduced the expression profile of the Atg5–Atg12 protein complex as well as lipidated LC3-II and unlipidated LC3-I during bacterial infection." (PMID 32064256, 2019). "Likewise, the levels of unlipidated and lipidated LC3 in addition to the autophagy-related Atg5–Atg12 protein complex were reduced during infection as presented by immunoblotting and immunofluorescent assays." (PMID 32064256, 2019). "As expected, ATG5, Beclin-1, ATG7 and ATG16L1 deficiency led to impaired conversion of endogenous LC3-I to LC3-II and decreased number of LC3 puncta following SH0165 infection." (PMID 31106159, 2019). "To assess whether this interaction occurs during infection, we investigated the presence of ATG5-12/16L1 complex by in situ proximity ligation assay (PLA)." (PMID 30286180, 2018). "Moreover, it has also been demonstrated that pre-infection autophagic inhibition via Atg5 knockdown in bone-marrow macrophages resulted in an increase in L. major parasite burden." (PMID 30158914, 2018).
infection (continued). "Atg5 or autophagy deficient plasmacytoid dendritic cells was failed to produce IFN-α in response to infection with vesicular stomatitis virus (VSV)." (PMID 28748360, 2017). "Even at higher MOIs, ATG5−/− MEFs still showed significant block of infection." (PMID 26248741, 2015). "Another possibility for the reason of resistance of ATG5−/− cells to HSV-2 infection may be attributed to an aberrant proinflammatory cytokine response to infection in these cells." (PMID 26248741, 2015). "qPCR assay also showed that ATG5 knockout in cells dramatically diminishes the infection." (PMID 26248741, 2015). "We found that ATG5-indepdendent autophagy, unlike canonical autophagy, does not appear to use two proteins associated with xenophagy during infection." (PMID 23966861, 2013). "Therefore, in the older leaves of atg5 mutant infection with Pst DC3000 (AvrRps4) leads to chlorotic cell death spreading to all the leaves." (PMID 24023671, 2013). "Finally, a potential link between autophagy and disease was observed in a study of genetic polymorphisms linked to chronic Q fever, where SNPs in ATG5 and MAP1LC3A were more commonly associated with controls, suggesting that autophagy promotes infection or more severe disease." (PMID 37645379, 2023). "Furthermore, the most severe splenic histopathological changes were observed in the control mice at 72 h after infection, whereas there were no histopathological changes in the spleens of the Atg5-deficient mice." (PMID 33036147, 2020). "After 24 h of infection, both NS1 and M2 gene expression were significantly lower in ATG5−/− MEFs compared to WT MEFs, suggesting that autophagy is important for viral RNA synthesis, although ATG5-deficient cells may also undergo more apoptosis." (PMID 32512864, 2020). "Notably, targeting of Lpg2936 by RNAi restored the expression of autophagy-related genes Atg7 and LC3B during infection and increased the protein level of the Atg5–Atg12 complex, unconjugated LC3-I, and conjugated LC3II proteins when compared to control-transfected and -infected macrophages." (PMID 32064256, 2019). "Notably, deletion of Rv1468c or substitution of Rv1468c with L65G mutant in Mtb increased bacterial loads in the lungs of the control mice, but not the Atg5-deficient mice, at 2 and 3 weeks post-infection." (PMID 31036822, 2019). "To determine whether the autophagy pathway can be induced upon RGDV infection, we first monitored the expression of 3 autophagy-related genes (Ulk1/Atg1, Atg5 and Atg8) in continuous cultured vector cells in a monolayer (VCM) derived from R. dorsalis using an RT-qPCR assay." (PMID 29125860, 2017). "Moreover, they detected strong colocalization between NS5B and ATG5 that is temporally restricted to early time points of infection, suggesting that NS5B/ATG5 interaction could be necessary for the establishment of HCV replication but not to maintain it." (PMID 21994783, 2011). "Inhibition of autophagy after infection resulted in increased p62 levels and decreased Beclin-1, ATG7, and ATG5 levels, similar to the response to IFITM3 knockdown, whereas overexpression of IFITM3 had the opposite effect." (PMID 40681213, 2025). "With ATG5 and ATG7 KO cell lines, cells have to adapt to survive during the amplification procedure following infection." (PMID 39851574, 2025). "Transcriptome analysis (accession numbers: PRJNA597582 and PRJNA597542) was conducted on cells transfected with either ATG5 or empty vector, followed by GCRV infection." (PMID 40454785, 2025).
infection (continued). "The autophagy-related marker proteins LC3B, ATG5, and BECN1 were upregulated post-infection, whereas SQSTM1 was downregulated, indicating that FAdV-4 infection enhances autophagic flux and induces complete autophagy." (PMID 40130861, 2025). "In this study, infection by C. parvum up-regulated the ratio of LC3B II to LC3B I, p62, Beclin-1, ATG7, and ATG5." (PMID 40681213, 2025). "In CVB3-infected ATG5 KO cells, VP1 protein expression was detected at 6 h post-infection, similar to WT cells." (PMID 41471369, 2025). "PcLVs display LC3 on single membranes are transiently induced after 1 h of infection and are dependent on several autophagy-related factors including SQSTM1, CALCOCO2, ATG5, and C-terminal WD domain of ATG16L1." (PMID 40910070, 2025). "We further analyzed the transcriptome data from cells transfected with either ATG5 or empty vector, followed by GCRV infection." (PMID 40454785, 2025). "Our results indicate that after the infection autophagic genes [Beclin-1 (p ≤ 0.03), UVRAG (p ≤ 0.03), Atg5 (p ≤ 0.01), Atg12 (p ≤ 0.01) and Atg16L (p ≤ 0.03)] are upregulated in contrast to the control group." (PMID 39845048, 2024). "Inactivation of Atg5 in myeloid lineage renders mice excessively susceptible to acute infection with Mycobacterium tuberculosis attributed to excessive inflammation 35,46,53–56, which did not extend to other phases of infection as tested here in a murine model of latent tuberculosis 77–79." (PMID 39026874, 2024). "In nonselective macroautophagy, various external stimuli including pathogen infection, nutrient deprivation, and radiation therapy enhance autophagy by upregulating autophagy mediators such as ATG3, ATG5, ATG12, and ATG16L1." (PMID 37180758, 2023). "ATG5 and ATG7 transcript levels were only slightly increased at 24 h post-infection, and this increase was essentially detected at 48 h post-infection." (PMID 36298785, 2022). "Specifically, we observed changes in gene expression of key autophagy genes Atg5 and p62/SQSTM1 accompanying ZIKV-infection and replication in human primary placental trophoblasts when compared to mock-infected controls." (PMID 37431450, 2021). "While atg2 mutants displayed less HR-PCD and ATG4, ATG5 inhibited the occurrence of HR-PCD, ATG6 antisense plants displayed enhanced HR-PCD during pathogen infection." (PMID 34829975, 2021). "A time-course coculture experiment was performed with Mock-, ATG5- and ATG7-KO Hep3B cells infected with H. hepaticus and its CDT corresponding ΔCDT strain and the effects of the infection following gene extinction were analyzed." (PMID 33662035, 2021). "Infection of RAW 264.7 macrophages with ΔPE_PGRS20 and ΔPE_PGRS47 resulted in increased Atg5 and decreased p62 (SQSTM1) and phospho-Unc-51-like autophagy-activating kinase 1 (Ulk1) compared to wild-type M. tuberculosis infection." (PMID 34346699, 2021). "Treatment with autophagy inhibitors or silencing of ATG5, ATG7, and ATG8h promoted TLCYnV infection in solanaceous plants." (PMID 32373106, 2020). "Indeed, C4 does not cause any reduction in infection in Atg5- and LC3-depleted host cells." (PMID 33214643, 2020). "Quantification of protein band intensity validated the significant reduction of the autophagy-related Atg5–Atg12 complex, LC3-I, and LC3-II following infection." (PMID 32064256, 2019). "We next measured the expression of an autophagy gene, Atg5, known to negatively regulate antiviral immune responses in Wt, and TLR7−/− pLN and found that Atg5 expression is reduced at a comparable level in pLN of Wt and TLR7−/− mice after infection." (PMID 30930901, 2019). "Recently, it has been shown that human neutrophils undergo autophagy following in vitro infection with Streptococcus pneumoniae that depends on type III PI3K and ATG5 and enhances the rate of neutrophil phagocytosis of bacteria." (PMID 30234114, 2018).